MTOR (mechanistic target of rapamycin kinase)
Diseases named in the same sentence as MTOR in open-access papers (continued):
Sharing a sentence is not in itself a finding about the gene and the disease.
cardiac hypertrophy (continued). "We found that allosteric activation of the BCKDH complex by mitolnc is critical to reduce local concentrations of leucine in cardiomyocytes, thereby preventing unwanted mTOR activation and cardiac hypertrophy." (PMID 38567728, 2024). "MiR-199a induces cardiac hypertrophy through mammalian target of rapamycin (mTOR) signaling pathway." (PMID 39850481, 2024). "Increased concentrations of leucine are known to activate mTOR signaling, the latter being a well-characterized pathway in the induction of cardiac hypertrophy." (PMID 38567728, 2024). "Existing studies have shown that cardiac hypertrophy can be inhibited by suppressing the Akt/mTOR signaling pathway." (PMID 39408627, 2024). "In a PTPN11-mutant murine NSML model, treatment with rapamycin, an mTOR pathway inhibitor, ameliorated myocardial hypertrophy." (PMID 39202376, 2024). "For example, resveratrol suppressed chronic intermittent hypoxia-induced cardiac hypertrophy by targeting the Akt/mTOR pathway." (PMID 39408627, 2024). "NLRC5 overexpression improves cardiac hypertrophy by inactivating the mTOR pathway, thereby increasing autophagy." (PMID 39519229, 2024). "Kyoto Encyclopedia of Genes and Genomes (KEGG) analysis indicated that the 566 overlapping genes were mainly enriched in signaling pathways associated with cardiac hypertrophy, such as AMPK, MAPK, and mTOR pathways." (PMID 38810124, 2024). "The Akt/mTOR signaling pathway has been extensively documented as a key mediator in the stimuli that induce cardiac hypertrophy, driving both adaptive and maladaptive cardiac growth." (PMID 39408627, 2024). "Consistently, deletion of MIF exacerbated pressure overload‐induced cardiac hypertrophy via activating mTOR signaling and mitigating autophagy." (PMID 38924383, 2024). "Akt was activated via phosphorylation of T308, which further activated the downstream GSK-3β/mTOR/p70S6K signaling pathway to promote the synthesis of hypertrophic markers and fibrin, which in turn led to cardiac hypertrophy and dysfunction." (PMID 39408627, 2024). "According to them, miR-17-5p targets mitofusin 2 (MFN2) to activate the PI3K/AKT/mTOR axis, thus reducing autophagy and promoting pathological cardiac hypertrophy." (PMID 38256030, 2024). "The Akt-GSK3β/mTOR signaling pathway is deeply involved in the progress of cardiac hypertrophy and remodeling." (PMID 38481817, 2024). "Inhibition of mTOR with rapamycin can attenuate pathological cardiac hypertrophy and improve the function of aging heart via inhibition of the cardiac proteasome activity." (PMID 39086659, 2024). "The mTOR/p70S6K pathway plays an important role in the development of pathological cardiac hypertrophy." (PMID 38744811, 2024). "This study also observed that following rapamycin addition to inhibiting the activity of mTOR activity, the effect of Apelin-13 on improving cardiac hypertrophy was significantly reduced and that the expression of MYH7 was significantly increased." (PMID 36742144, 2023). "The accumulated BCAAs can activate mTOR signal and accelerate the occurrence and development of myocardial hypertrophy." (PMID 36824437, 2023). "The distinct mechanism of action by which mTOR inhibition reduces cardiac hypertrophy remains to be fully elucidated; however, it has been previously demonstrated that inhibition of mTOR reduces cellular anabolic activities." (PMID 37893908, 2023). "They stated that endurance training decreased GSK3β and thus increased mTOR levels, which is an important factor in cardiac hypertrophy." (PMID 37274326, 2023). "In rats, elevated miR-29a in the heart activated the AKT/mTOR pathways, which lead to cardiac hypertrophy and eventually HF." (PMID 37035745, 2023). "Overstimulation of mTOR signaling under stress conditions promotes pathological cardiac hypertrophy." (PMID 37107252, 2023).
cardiac hypertrophy (continued). "In isoproterenol-induced cardiac hypertrophy and fibrosis rat model, curcumin played an obvious therapeutic role via mammalian target of rapamycin (mTOR)/autophagy axis." (PMID 37191432, 2023). "Studies have shown that the mammalian target (mTOR)/P70 ribosomal S6 protein kinase (p70S6K) pathway is involved in stimulating protein synthesis and regulating cardiac hypertrophy." (PMID 36528874, 2023). "It has also been reported that TLR4 plays an important role in the regulation of cardiac hypertrophy, and that TLR4 participates in cardiac hypertrophy regulation through the mTOR signaling pathway." (PMID 35855640, 2023). "Multitudinous studies have shown that AMPK/mTOR pathway can regulate the occurrence and development of atherosclerosis, myocardial hypertrophy, myocardial I/R and other diseases." (PMID 37063954, 2023). "As expected, the inhibitory effects of Trim44 KO on pathological cardiac hypertrophy induced by ISO treatment were exerted by suppressing the AKT/mTOR/GSK3β/P70S6K signaling pathway." (PMID 35855640, 2023). "Collectively, these results show that GPR30 activation protected TAC induced cardiac hypertrophy in the OVX mice by regulating autophagy through the AKT/mTOR pathways." (PMID 36674423, 2023). "mTOR inhibition has been suggested to have a helpful effect on atherosclerosis, heart failure and myocardial hypertrophy." (PMID 37108307, 2023). "Chaer-PRC2 interaction is transiently promoted by the mammalian target of rapamycin (mTOR) pathway upon stress or hormonal stimuli and ultimately results in the induction of the genes responsible for heart hypertrophy." (PMID 36760365, 2023). "Calcineurin inhibitors promote cardiac hypertrophy, hypertension, dyslipidemia, and vascular remodeling, while mTOR inhibitors have an anti-proliferative effect with attenuation of cardiac hypertrophy and vascular remodeling despite promoting dyslipidemia." (PMID 36211586, 2022). "In CBK animals, on the other hand, repression of BCAA catabolism genes was observed, leading to increased cardiac BCAA levels and, ultimately, an exacerbated activation of mTOR signaling and cardiac hypertrophy." (PMID 36557311, 2022). "Multiple studies have demonstrated that rapamycin, a specific mTOR inhibitor, attenuates pathological cardiac hypertrophy." (PMID 35461308, 2022). "Suppression of mTOR with rapamycin avoids cardiac hypertrophy, advocating that mTOR plays a pivotal role in cardioprotection." (PMID 35628576, 2022). "We also investigated that mTOR inhibitors can postpone testosterone-induced OVXSHR cardiac hypertrophy." (PMID 34874016, 2022). "Hyperactivation of mammalian target of rapamycin (mTOR) signaling drives cardiac hypertrophy in MKK6 KO mice." (PMID 35971771, 2022). "In another study of pressure-overload stress induced cardiac hypertrophy, it was demonstrated that Rapamycin decreased the expression of the Akt/mTOR/P70S6K1 pathway in a MEK/ERK/Beclin-1 signalling dependent manner." (PMID 35821839, 2022). "Ketone bodies have a protective effect on cardiac hypertrophy and diabetic nephropathy by inhibiting mTOR signaling." (PMID 35055179, 2022). "In this process, activation of AMPK by metformin and inhibition of mTOR by rapamycin protects the heart from cardiac hypertrophy by triggering autophagy induction." (PMID 35390228, 2022). "mTOR inhibition has also been shown to improve testosterone-induced myocardial hypertrophy in hypertensive rats, together supporting the potential sex-specific effects of mTOR on cardiovascular health." (PMID 35712086, 2022). "Cardiac hypertrophy in MKK6 KO mice is reverted by knocking out either p38γ or p38δ or by inhibiting the mTOR pathway with rapamycin." (PMID 35971771, 2022). "Although these findings consolidated the notion of therapeutic modulation of LKB1/AMPK/mTOR signaling as a valuable strategy for preventing cardiac hypertrophy and HF, effective pharmacological treatments aimed at this end remain to be developed." (PMID 35592411, 2022).
cardiac hypertrophy (continued). "It has been suggested that angiotensin II (Ang II)-mediated mTOR phosphorylation in neonatal rat cardiomyocytes and mTOR acted as the upstream modulator of NRF2 in Ang II-induced cardiac hypertrophy." (PMID 36430296, 2022). "It is well-known that mammalian target of rapamycin (mTOR) signaling is involved in the pathogenesis of cardiac hypertrophy and diabetic nephropathy." (PMID 35055179, 2022). "In the TAC model, inhibition of PTEN degradation led to AKT/mTOR inactivation and AMPK signal activation, thereby ameliorating cardiac hypertrophy and dysfunction caused by pressure overload." (PMID 36204518, 2022). "As an inhibitor of the Akt/mTOR pathway, we expected metformin to reduce cardiac hypertrophy, as previously reported in both mice and humans." (PMID 36359302, 2022). "In particular, downregulation of CTRP9 gene leads to reduced AMPK phosphorylation and increased mTOR phosphorylation, inducing cardiac hypertrophy, fibrosis, apoptosis and oxidative stress in the context of obesity induced cardiac hypertrophy." (PMID 36012897, 2022). "Decreased PI3K expression and AKT phosphorylation can delay renal fibrosis through the PI3K/AKT/mTOR signaling cascade in HN rat renal hypertrophy model." (PMID 36204234, 2022). "In fact, reduced mTOR activity through rapamycin supplementation alleviated age-dependent cardiac hypertrophy and diastolic dysfunction in mice as well as reduced dysregulated mitochondria and ROS generation." (PMID 35821839, 2022). "It is reported that IGF-1, PI3K, Akt, and mTOR signaling are also involved in exercise-induced cardiac hypertrophy." (PMID 36093083, 2022). "A recent study determined that GPR39, as an inhibitor of AMPK, increases after TAC to activate mTOR and promotes cardiac hypertrophy." (PMID 36204518, 2022). "In the heart, pharmacological inhibition of mTOR with rapamycin reverses cardiac hypertrophy induced by Akt overexpression." (PMID 33664668, 2021). "Among them, the insulin growth factor 1 receptor (IGF1R)-phosphatidylinositol 3-kinase (PI3K)–protein kinase B (AKT)-mammalian target of rapamycin (mTOR) axis is considered as one of the most important signaling cascades governing adaptive cardiac hypertrophy." (PMID 34208388, 2021). "In order to unravel the molecular mechanism underlying the PE-induced increase in protein synthesis and ultimately cardiac hypertrophy and contractile failure, we investigated the effect of PE on the Pi3K/Akt/mTOR-pathway and on the PKD1-HDAC5 axis." (PMID 33807195, 2021). "As a consequence of Ly6Clow macrophage polarization by topiramate treatment, the Areg-induced Akt/mTOR signaling pathway was activated, which resulted in myocardial hypertrophy." (PMID 34135897, 2021). "Specifically, we have shown that unlike hypertension-induced and ischemia-induced models, the cardiac hypertrophy triggered by CPT2 deficiency is resistant to attenuation by rapamycin, an mTor inhibitor, and by trichostatin A, a deacetylase inhibitor." (PMID 33757734, 2021). "In the present study, we aim to investigat its potential regulation and the possible contribution of its predicted target UBQLN1 and the related mTOR signaling pathway to cardiac hypertrophy progression." (PMID 34515612, 2021). "Taken together these data establish a critical connection between SIRT6, mTOR signaling, protein synthesis and cardiac hypertrophy." (PMID 33855020, 2021). "Cardiomyopathy was validated by cardiac hypertrophy, fibrosis, oversized myocytes, and mTOR upregulation in a rat model of cafeteria diet-induced developmental obesity." (PMID 33716957, 2021). "Repression of mTOR with rapamycin can inhibit protein synthesis and repress cardiac hypertrophy induced by different pathological stress." (PMID 34059001, 2021). "This indicates that the protective effects of QC on myocardial hypertrophy involve the inhibition of mTOR signaling pathway." (PMID 34007292, 2021).
cardiac hypertrophy (continued). "More importantly, the activated Akt/mTOR signal pathway during cardiac hypertrophy was inhibited by EGCG treatment." (PMID 34607503, 2021). "It is notable that mTOR activation alone is insufficient and requires coordination with other signaling pathways effectors to promote cardiac hypertrophy." (PMID 34540911, 2021). "MiR-99a suppresses aortic banding-induced cardiac hypertrophy targeting the mTOR/P70/S6K signaling pathway." (PMID 34540911, 2021). "Previous studies have shown that exercise can moderately upregulate protein kinase B, improve myocardial metabolism through downstream mTOR (mammalian target of rapamycin, mTOR), protect cardiac functions, and delay cardiac hypertrophy." (PMID 34442203, 2021). "TH-dependent cardiac hypertrophy was described as physiological hypertrophy mediated by the phosphoinositide 3-kinase/protein kinase B/mammalian target of rapamycin (PI3K/AKT/mTOR) signaling pathway." (PMID 34395557, 2021). "A previous study showed that KLF15 suppressed isoproterenol-induced cardiac hypertrophy and fibrosis by inhibiting mTOR signaling." (PMID 33869197, 2021). "Recent research is dedicated to the investigation of downstream effector pathways involved in the progression of cardiac hypertrophy and heart failure, Akt and mammalian target of rapamycin (mTOR) are included." (PMID 34607503, 2021). "In vivo, the Mybpc3-KO mouse model given AZD2014 to dually inhibit mTORC1/2, revealed that mTOR is involved in the regulation of cardiac hypertrophy and in the control of vital cellular processes necessary for maintenance of cardiac function." (PMID 34674743, 2021). "Here, we investigated the expression of mTOR in hypertrophic cardiomyocytes using western blot analysis and found that the expression and phosphorylation of mTOR as well as the phosphorylation of p70S6K were upregulated in response to cardiac hypertrophy." (PMID 34515612, 2021). "As expected, seven significantly enriched disease hallmark pathways that were identified, including MAPK, mTOR, and the chemokine signaling pathway, are associated with HTN-induced renal damage, cardiac hypertrophy, and vascular remodeling, respectively." (PMID 34575987, 2021). "Though generally thought to positively correlate with the pathogenesis of cardiac hypertrophy, there are numerous mysteries about the regulation and function of mTOR." (PMID 34977198, 2021). "Partial genetic deletion or pharmacological suppression of mTOR has been found to persistently ameliorate cardiac hypertrophy induced by AB." (PMID 34540911, 2021). "To explore the underline mechanism of EGCG treatment for cardiac hypertrophy, we examined the AKT/mTOR signalling pathway and the phosphorylation of ERK." (PMID 34607503, 2021). "Activation of mTOR signaling has been involved in the pathogenesis of cardiac hypertrophy; however, cardiac-specific ablation of raptor impairs adaptive hypertrophy, but causes heart failure in mice." (PMID 34977198, 2021). "Emerging evidence shows that epigenetic reprogramming participates in the contribution of mTOR during cardiac hypertrophy." (PMID 34540911, 2021). "The Akt/mTOR pathway contributes significantly to the activation of mTORC1 during the development of cardiac hypertrophy, while mTORC2 is involved in the regulation of cell survival, growth, and proliferation in cardiomyocytes." (PMID 34674743, 2021). "The mechanistic target of rapamycin (mTOR) growth pathway is a critical regulator of cardiac hypertrophy." (PMID 33757734, 2021). "The genetic and pharmacological downregulation of class I HDACs blunts pathological cardiac hypertrophy by inhibiting TSC2-dependent mTOR signaling." (PMID 34540911, 2021).
cardiac hypertrophy (continued). "Taken together, our results reveal that chronic upregulation of the HBP under hemodynamic stress induces pathological cardiac hypertrophy and heart failure through persistent activation of mTOR." (PMID 32286306, 2020). "In aged mice, knocking out and inhibiting mTOR can prolong survival and inhibit cardiac hypertrophy." (PMID 33062700, 2020). "It was also demonstrated that ALS treatment suppressed the mTOR and apoptosis pathways in the pathological process of cardiac hypertrophy." (PMID 31994601, 2020). "A great deal has also been discovered regarding upregulation of translational output in cardiac hypertrophy coming from studies in mice of mTOR function and its regulatory components." (PMID 32164190, 2020). "Activation of mTOR serves as the main mechanism of pressure overload-induced cardiac hypertrophy; this signaling pathway is also involved in age-related hypertrophy." (PMID 32863202, 2020). "Herein the present study, we identified CPA4 as an indirect upstream activator for the mTOR-S6K1 signaling pathway and activated mTOR during cardiac hypertrophy." (PMID 32347291, 2020). "The aim of the present study was to investigate the role of ALS in mammalian target of rapamycin (mTOR) and apoptosis signaling using in vivo and in vitro models of cardiac hypertrophy." (PMID 31994601, 2020). "Comparison of physiological versus pathological cardiac hypertrophy in mice reveals an increase in mTOR activity following 6 weeks of exercise training resulting in physiological growth." (PMID 32164190, 2020). "SIRT3 can active the activity and nuclear translocation of FOXO3α, thereby inhibiting mTOR and Rho/Rho kinase signaling and preventing cardiac hypertrophy." (PMID 32724473, 2020). "Subsequent work indicates that rapamycin inhibition of mTOR can partially restore normal heart size and function in mice with established cardiac hypertrophy." (PMID 32164190, 2020). "Sesn2 knockout or aging enhances pressure overload-induced cardiac hypertrophy through excessive activation of mTOR, which is the key regulator of myocardial metabolism." (PMID 32863202, 2020). "Other evidence has demonstrated that pharmacological AMPK activation attenuates the development of cardiac hypertrophy by inhibiting protein synthesis through the inactivation of the mammalian target of rapamycin (mTOR) signaling pathway." (PMID 32372974, 2020). "Astragaloside IV can reduce oxidative stress and delay myocardial hypertrophy by inhibiting the AMPK/mTOR pathway, thereby improving myocardial damage." (PMID 33134388, 2020). "Intriguingly, mTOR signaling also plays a potential role in cardiac hypertrophy and fibrosis progression." (PMID 31994601, 2020). "mTOR is a pivotal regulator for protein synthesis and cardiac hypertrophy via activating the ribosomal protein S6K1." (PMID 32347291, 2020). "In response to AngII, MIAT acts as a molecular sponge of miR-93 which participates in the inactivation of the PI3K/Akt/mTOR pathway via targeting TLR4 in AngII-induced cardiac hypertrophy." (PMID 32754048, 2020). "During the development of cardiac hypertrophy, excessive activation of mTOR leads to increased mitochondrial damage, as well as reductions in glucose metabolism, fatty acid metabolism, and oxygen metabolism." (PMID 32863202, 2020). "Ang II infusion activates several signaling pathways including AKT/mTOR, TGF-β/Smad2/3, and NF-κB through Ang II type receptor (AT1R), causing hypertrophy, fibrosis, inflammation, and oxidative stress, finally leading to cardiac hypertrophy and AF." (PMID 32595507, 2020). "In particular, MIAT knockdown can enhance miR-93 and inactivate the PI3K/Akt/mTOR pathway via regulating the TLR4 in angiotensin II-induced cardiac hypertrophy." (PMID 32605220, 2020). "Obviously, as a sensor for the change in the energy metabolic substrate and an inhibitor of autophagy in cardiac hypertrophy, mTOR is an important target for treating cardiac hypertrophy." (PMID 33328993, 2020).